MTOR (mechanistic target of rapamycin kinase)
Diseases named in the same sentence as MTOR in open-access papers (continued):
Sharing a sentence is not in itself a finding about the gene and the disease.
breast cancer (continued). "The recruitment of Runx2 on mTOR promoter coupled with Runx2-dependent expression of mTORC2 component Rictor defined Runx2 function in pAkt-mediated survival of invasive breast cancer cells." (PMID 24479521, 2014). "Combinations of Herceptin with pertuzumab, or T-DM1 and mTOR inhibitors added to an aromatase inhibitor are new therapeutic approaches for the treatment of HER2+ breast cancers." (PMID 25051360, 2014). "In breast cancer development, arachidonic acid is a critical molecule that has been shown to activate mTOR and increase the activity of VEGF." (PMID 26413184, 2014). "Genomic data obtained through the Breast Cancer Gene Expression Miner v3.0 was analyzed for mTOR signaling components (Rictor, Raptor, and Rheb), ERα, and PgR." (PMID 25283550, 2014). "Recent reports have demonstrated that the PI3K/AKT/mTOR pathway is frequently altered in human breast cancer and that TNBC cells exhibit alterations in PTEN or loss in INPP4B." (PMID 25209360, 2014). "Herein we confirm that targeted combinatorial therapy that simultaneously inhibits mTOR signaling and glycolytic metabolism is a viable strategy for the treatment of aggressive primary breast cancer." (PMID 25436981, 2014). "Poly (ADP-ribose) polymerase (PARP), EGFR, and mTOR inhibitors are among the therapeutic agents being studied in patients with TNBC and BRCA1-associated breast cancers." (PMID 24507701, 2014). "Our findings suggest that inhibiting the mTOR-FASN axis is a promising new strategy for treating ER/HER2-positive breast cancer." (PMID 24866893, 2014). "We used a PI3K/AKT pathway inhibitor and an mTOR inhibitor to probe the role of the PI3K/AKT/mTOR pathway on FASN expression in ER+/HER2+ breast cancer cells." (PMID 24866893, 2014). "FASN expression has been reported to be regulated by the human epidermal growth factor receptor HER2 oncogene (erbB2) through phosphatidylinositol 3-kinase (PI3-K)/Akt in breast cancers as well as by mTOR signaling pathways in colorectal cancer cells." (PMID 25255125, 2014). "There is currently considerable interest in the use of mTOR inhibitors in the treatment of breast cancer in general, and everolimus has been considered as a candidate drug for triple-negative breast cancer." (PMID 24724101, 2014). "These preclinical data support the clinical observation that estrogen receptor alpha (ERα)-positive metastatic breast cancer patients with prior exposure to aromatase inhibitors derive substantial benefit from the addition of an mTOR inhibitor." (PMID 24447434, 2014). "NVP-BEZ235 inhibits the activation of PI3K/Akt and mTOR signaling, which is important for cell survival, and consequently induces cell death in non-small lung cancer and breast cancer cells." (PMID 24743574, 2014). "It was previously demonstrated in breast cancer cells that nutrient starvation results in an increase in autophagy through inhibition of mTOR." (PMID 25526515, 2014). "Recent data indicate that combining endocrine therapy in breast cancer with mTOR inhibitors is effective to eliminate cancer cells." (PMID 25209360, 2014). "Our ex vivo data also showed a statistically significant inverse correlation between expression of mTOR and miR-99a in breast cancer tissues and cell lines." (PMID 24637915, 2014). "Phosphorylation of ER by mTOR’s downstream target p70S6K is potentially important in deciding personalized treatment for ER + breast cancers in the resistance to Tamoxifen." (PMID 25034939, 2014). "Inhibition of mTOR activity by rapamycin sensitized Aur-A-overexpressed breast cancer cells to metabolic stress-induced cell death." (PMID 25115395, 2014). "MID1 was recently shown to mediate the ubiquitin-dependent degradation of α4, a regulator of mTOR and cell-cycle progression, which is highly expressed in breast cancer." (PMID 24944582, 2014).
breast cancer (continued). "Cellular metabolism, AMP-activated protein kinase (AMPK) and mammalian target of rapamycin (mTOR) pathway signaling, as well as autophagy induction was evaluated in breast cancer cell lines treated with 8-Cl-Ado." (PMID 24628795, 2014). "The mTOR pathway is frequently activated in various cancers, including breast cancer, which plays a critical role in tumor growth and metastasis." (PMID 24553191, 2014). "The results showed that the inhibition of breast cancer cell proliferation and the acceleration of apoptosis by miR-99a mimics were rescued by restoration of mTOR expression." (PMID 24637915, 2014). "Several studies have indicated that estrogen can induce activation of the mTOR pathway in estrogen target tissues including breast cancer cells." (PMID 24887419, 2014). "We evaluated FASN and mTOR expression in breast cancer cell lines by western blotting and indirect immunofluorescence." (PMID 24866893, 2014). "This study has further characterized that miR-99a is a tumor suppressor by directly targeting mTOR in human breast cancers." (PMID 24637915, 2014). "Targeting cellular metabolism by metformin in combination with everolimus, a mTOR inhibitor, has been reported to sensitize chemotherapy against breast cancer cells." (PMID 24457597, 2014). "We are optimistic that mTOR inhibitors will broadly affect the treatment of breast cancer, especially TNBCs." (PMID 24708766, 2014). "We show here for the first time, as far as we know, that phosphorylation of mTOR at serine 2448 can be induced by estrogen in a time dependent manner in MCF7 breast cancer cells and mTOR can be coimmunoprecipitated with ERα in these cells." (PMID 24887419, 2014). "In the MCF-7 breast cancer cell line, mTOR activity is thought to be responsible for the constitutive activity of Akt, and inhibition of mTOR activity restores response to the antiestrogen tamoxifen." (PMID 25232533, 2014). "Pre-clinical data were supportive of the use of current mTOR antagonists alongside endocrine therapy in breast cancer which resulted in a number of clinical trials using such combination therapies." (PMID 24457069, 2014). "EGFR overexpression is well-studied in breast cancer, and EGFR-driven signaling pathways such as PI3K/AKT/mTOR, JAK/STAT, and Ras/Raf/MAPK were associated with cell proliferation and survival." (PMID 24864132, 2014). "We used luciferase reporter assays to explore the effect of an mTOR inhibitor on FASN transcription in ER+/HER2+ breast cancer cells." (PMID 24866893, 2014). "Based on these findings, we investigated the molecular role for mTOR in ERα signaling regulation in breast cancer." (PMID 25283550, 2014). "To further confirm that miR-99a inhibits mTOR expression in breast cancer, we analyzed the protein levels of mTOR from ten pairs of breast cancer and normal tissue specimens by immunoblot." (PMID 24637915, 2014). "The phosphotidyl-inositol 3 kinase (PI3K)/AKT/mTOR pathway is known to be dysregulated in a wide spectrum of human cancers including breast cancer." (PMID 24684785, 2014). "The PI3K/Akt/mTOR pathway is a complex network with multiple components, and is frequently deregulated in human breast cancer." (PMID 25209360, 2014). "The results indicated that mTOR was required for the miR-99a-dependent cell viability and apoptosis effect in breast cancer cells." (PMID 24637915, 2014). "Recently, EGFR, mTOR, and Poly (ADP-ribose) polymerase (PARP) inhibitors were among the therapeutic agents being studied in patients with TNBC and BRCA1-associated breast cancers." (PMID 24507701, 2014). "Taken together, these results have demonstrated that miR-99a antitumor activity is achieved by targeting the mTOR/p-4E-BP1/p-S6K1 pathway in human breast cancer cells." (PMID 24637915, 2014). "At equimolar concentrations NVP-BEZ235 exerted relatively more potent antitumor effect compared with mTOR inhibitors (temsirolimus, everolimus) against bladder and breast cancer cells." (PMID 24969552, 2014).
breast cancer (continued). "A FASN inhibitor and an mTOR inhibitor synergized to diminish the malignant phenotype of ER+/HER2+ breast cancer cells." (PMID 24866893, 2014). "Initial characterization ex vivo of primary mammary tumor cells confirmed that inhibition of mTOR by AZD8055 significantly reduced AKT, mTORC1/mTORC2 and glycolytic activities." (PMID 25436981, 2014). "Our current data demonstrate that reduced miR-99a expression in breast cancer tissues and cells result in mTOR overexpression, which in turn contributes to breast cancer development." (PMID 24637915, 2014). "In breast cancer, 44.9% of tumor tissues had increased levels of mTOR, while 71.9% of invasive breast cancer tissues expressed high level of phosphorylated S6K1 protein." (PMID 24637915, 2014). "The phosphatidyl inositol 3-kinase/mammalian target of rapamycin (PI3K/mTOR) pathway is an important target for therapies for numerous cancers such as lung carcinoma, thyroid carcinoma, breast cancer, gastrointestinal carcinoma, and bladder carcinoma." (PMID 24647338, 2014). "Other studies reported overexpression of mTOR and its substrate in breast cancer tissue and cell lines." (PMID 24637915, 2014). "Here, we sought to determine if the Akt/mammalian target of rapamycin (mTOR) pathway and the autophagic process play any specific role in the regulation of the anticancer properties of anthricin in breast cancer cell lines." (PMID 23818925, 2013). "Results presented in previous subsections of this work suggest that SFN inhibits mTOR signaling in other breast cancer cells." (PMID 23389114, 2013). "Here, we investigated the effect of anthricin on autophagy and mammalian target of rapamycin (mTOR) signaling as anticancer actions in breast cancer cells." (PMID 23818925, 2013). "mTOR signaling also makes a significant contribution to the maintenance of TICs in breast cancer and prostate cancer." (PMID 23922888, 2013). "On the other hand, breast cancer cells with PTEN deficiency were found to be resistant to PI3K inhibitors, PI3K/mTOR inhibitors or mTOR inhibitors whereas some of the PTEN-deficient breast cancer cell lines were sensitive to inhibitors of the PI3K pathway." (PMID 23459844, 2013). "Upregulation of the insulin-like growth factor/PI3K/AKT/mTOR pathway is one suggested mechanism behind PgR downregulation in breast cancer, despite a functional ER." (PMID 24131622, 2013). "In tandem with ongoing studies evaluating mTOR inhibitors in breast cancer, there is a tremendous amount of effort being placed in evaluating pan- and alpha-specific PI3 kinase inhibitors." (PMID 23662165, 2013). "mTOR inhibitors such as everolimus (RAD001) are effective in advanced breast cancer although toxicities will prevent its use as a preventive agent; rapamycin in animal models reduces tumour incidence and increases longevity." (PMID 24286369, 2013). "In preclinical studies with cell lines of non small cell lung, pancreatic, colon, and breast cancer combined inhibition of mTOR and EGFR resulted in a potentiation of anti cancer activity and resensitization of cell lines resistant to EGFR inhibitors." (PMID 22367239, 2013). "Inhibitors of signal molecules downstream of IGF-1R including PI3K/Akt/mTOR also reduced the ALDH+ population of breast cancer cells." (PMID 23663564, 2013). "ZNF703 overexpression in MCF-7 breast cancer cells activated the Akt/mTOR signaling pathway, downregulated ERα, and reduced the antitumor effect of tamoxifen." (PMID 23991038, 2013). "Analysis of STK11−/−/NIC mammary tumors revealed hyperactivation of mammalian target of rapamycin (mTOR) through both mTORC1 and mTORC2 pathways as determined by the phosphorylation status of ribosomal protein S6 and AKT." (PMID 23451056, 2013). "Several in vitro and in vivo preclinical studies have investigated the potential mTOR inhibitors in the prevention of breast cancer." (PMID 24069582, 2013).
breast cancer (continued). "Although not tested in the prevention of breast cancer yet, the recent findings on mTOR/S6K pathway make it a promising target for the prevention of breast cancer." (PMID 24069582, 2013). "In this regard recent studies have shed light on the complex interactions between the PI3K/AKT/mTOR, Ras/RafMAPK, and/or Wnt/ß-catenin signaling pathways governing tumor growth and metastasis in melanoma, colon cancer, breast cancer, and others." (PMID 23648148, 2013). "In conclusion, our most significant finding is that anthricin isolated from A. sylvestris inhibits Akt/mTOR signaling in breast cancer cells." (PMID 23818925, 2013). "The Akt/mTOR pathway has been identified as an important target in breast cancer research over the past 20 years." (PMID 23818925, 2013). "In fact, immunohistochemistry analysis of mammary tumors developed in our mice indicated that phosphorylation of Akt and mTOR is increased, suggesting that activation of Akt/mTOR pathway collaborates with Aurora-A, leading to cell transformation." (PMID 23383195, 2013). "We found that mTOR signaling and autophagy play important roles in the balance between cell death and cell survival induced by anthricin in breast cancer cells." (PMID 23818925, 2013). "The emerging evidence shows that the mTOR network is deregulated in cardiovascular disease, type-2 diabetes, and cancer, including breast cancer." (PMID 28239123, 2013). "Everolimus, an mTOR inhibitor approved for breast cancer, neuroendocrine tumors of pancreatic origin and subependymal giant cell astrocytoma, has been tested in GC patients in a phase II and phase III trial." (PMID 24088382, 2013). "Our findings suggest that IGF-1R and its signaling via PI3K/Akt/mTOR pathway are attractive targets for therapy directed against breast cancer stem/progenitors." (PMID 23663564, 2013). "We further examined the effects of disruption of the PI3K/Akt/mTOR pathway in the CSC population of breast cancer cells." (PMID 23663564, 2013). "The present study also showed that IIi inhibits mTOR activity and induces autophagy in breast cancer cells." (PMID 23761818, 2013). "mTOR inhibitors have also been investigated in a number of preclinical breast cancer prevention studies using mouse models." (PMID 24069582, 2013). "mTOR is considered a potential target for anti-tumor therapies due to its role in breast cancer progression." (PMID 23587222, 2013). "The comparison of energy-balance regimens, such as CR, and pharmacological interventions with well-established mTOR inhibitors has revealed that rapamycin conspicuously mimics CR in its ability to decrease the mammary tumor burden in obese animals." (PMID 23986086, 2013). "Taken together, our findings support the notion that IGF-1R signaling with activation of the downstream PI3K/Akt/mTOR pathway plays an important role in breast cancer progression by controlling both the maintenance of BCSCs and their EMT behavior." (PMID 23663564, 2013). "Our data support the notion that IGF-1R is a marker of stemness, and IGF-1R and its downstream PI3K/Akt/mTOR pathway are attractive targets for therapy directed against breast cancer stem/progenitors." (PMID 23663564, 2013). "Recent exciting clinical trial results in advanced estrogen receptor-positive (ER) breast cancer support mTOR activation is a major means of estrogen-independent tumor growth." (PMID 23301057, 2013). "Our data showed that anthricin treatment reduced the phosphorylation of Akt, S6K1, and mTOR, suggesting that anthricin inhibits the Akt/mTOR signaling pathway, thus inhibiting breast cancer growth." (PMID 23818925, 2013). "Early studies have shown that the mTOR signaling pathway is essential for the growth of estrogen-dependent luminal breast cancer cells." (PMID 23991038, 2013). "CCL5 activation stimulates the growth of MCF-7 breast cancer cells through an mTOR-dependent mechanism." (PMID 23946783, 2013).
breast cancer (continued). "The most frequently altered intracellular growth signalling pathway in breast cancer is PI3K/AKT/mTOR, which is suggested as a key driver of proliferation and survival, particularly in ER-positive tumours." (PMID 24131622, 2013). "Similar to human breast cancer, these tumours demonstrate high expression of mammalian target of rapamycin (mTOR)." (PMID 23587222, 2013). "Identification of a role for the mTOR signaling network in the reduction of cancer burden by dietary bean is highly relevant given that this pathway is deregulated in most human breast cancers." (PMID 28239123, 2013). "The results demonstrate that FAM83D has prognostic value for breast cancer patients and is a novel oncogene in breast cancer development that at least in part acts through mTOR hyper-activation by inhibiting FBXW7." (PMID 24344117, 2013). "Upregulation of the PI3K/AKT/mTOR pathway has been associated with decreased benefit from endocrine therapies in breast cancer, and recent studies support mTOR inhibitors as promising agents for overcoming endocrine resistance." (PMID 24131622, 2013). "Targeting mTOR has emerged as a new promising treatment strategy for several malignancies and recent data indicate that combining endocrine therapy in breast cancer with mTOR inhibitors is effective." (PMID 24131622, 2013). "Our previous work with human breast cancer cell lines showed that the combined inhibition of FGFR and ErbB receptors caused a complete loss of PI3K/Akt/mTOR pathway activity and a robust block in in vitro proliferation." (PMID 23343422, 2013). "The importance of PI3K/Akt/mTOR in BCSCs of clinical samples is consistent with findings from previously reported studies of breast cancer cell lines." (PMID 23663564, 2013). "The phosphatidylinositol 3-kinase (PI3K)/AKT/mammalian Target Of Rapamycin (mTOR) pathway is commonly deregulated in breast cancer and consequently, there is intense interest in the clinical development of agents that target this pathway." (PMID 23301057, 2013). "Activation of AMPK by these EGCG analogs resulted in the inhibition of cell proliferation, up-regulation of the cyclin-dependent kinase inhibitor p21, downregulation of the mTOR pathway, and suppression of stem cell population in human breast cancer cells." (PMID 23875169, 2013). "The common activation of the PI3K pathway in breast cancer has led to the development of compounds targeting the downstream effector, mTOR." (PMID 23468988, 2013). "The FLOT2-mediated stabilization of ErbB2 has been associated with tumorigenesis in stage I/II breast cancer tissues, which is reflected by reduced p-ErbB2 and p-Akt levels and hyperactivity of the PI3K/AKT/mTOR pathway in breast tumors." (PMID 23945257, 2013). "For example, 17-AAG abolished Akt activation and potentiated the mammalian target of rapamycin (mTOR) inhibitor, rapamycin, in breast cancer cells." (PMID 23840275, 2013). "Our previous studies demonstrated that α6β4 integrin stimulates eIF4E activity to promote translation of survival factor, VEGF via Akt/mTOR pathway in breast carcinoma cells under serum deprivation condition." (PMID 24180592, 2013). "Our results support the role of PI3K/mTOR pathway inhibitors for breast cancer treatment in HR-positive breast cancer." (PMID 23102376, 2012). "Wnt1 has been shown to require mTOR activation during breast cancer cell proliferation, to drive hair follicle proliferation and stem cell modulation, and to promote inflammatory cell survival during oxidant stress." (PMID 22388478, 2012). "This was in agreement with previously published data shown for the dual PI3K/mTOR inhibitor NVP-BEZ235 in breast cancer cells." (PMID 23300809, 2012). "It is therefore highly likely that multiple mechanisms (ER stress response, Akt signaling and mTOR pathway) are operating to inhibit the growth of human breast cancer cells." (PMID 22905241, 2012).